IL13RA2 (interleukin 13 receptor subunit alpha 2)
Diseases named in the same sentence as IL13RA2 in open-access papers (continued):
Sharing a sentence is not in itself a finding about the gene and the disease.
tumor (continued). "Based on preclinical promising results in murine models, a pilot study assayed the efficacy of IL-13Rα2-directed CD8+ cytotoxic T cells (NCT00730613) following tumor resection in three rGB patients." (PMID 38473776, 2024). "Since we have demonstrated that MDSCs and regulatory T cells express IL‐13Rα2,64 it is possible that CAR‐T cells with a high binding targeting structure (scFv‐IL‐13Rα2 as a payload) will have a better chance of demonstrating a robust anti‐tumour effect." (PMID 38685487, 2024). "In the current study, we report the development of a novel IL‐13Rα2‐specific CAR (IL‐13Rα2‐CAR‐T cells) with an improved scFv‐based antigen binding domain that provides better recognition of IL‐13Rα2 on the tumour cell surface." (PMID 38685487, 2024). "We reveal IL‐13Rα2 down‐modulation on tumour cells and induction of tumour cell killing as an important mechanism of tumour regression after CAR‐T cell contact mediated by interaction of CAR‐T cells with IL‐13Rα2 and its internalisation." (PMID 38685487, 2024). "A case report from a phase I clinical trial with CAR T-cell therapy targeting IL13Rα2 observed tumor regression in a recurrent multifocal GBM patient." (PMID 39599889, 2024). "Trial eligibility criteria included confirmed IL-13Rα2 tumor expression, Karnofsky Performance Score (KPS) ≥60 and life expectancy >4 weeks." (PMID 38454126, 2024). "The interleukin-13 receptor α2 (IL-13Rα2) and the erythropoietin-producing hepatocellular receptor A2 (EphA2) have been identified as playing crucial roles in tumor growth and progression." (PMID 38612592, 2024). "IL-13Rα2 CAR-T cells were locally injected into resected tumor cavities of three patients with rGBM." (PMID 39506843, 2024). "For example, dual targeting of HER2 and IL13Rα2 antigen in GBM revealed an anti-tumor potential of dual-targeting CAR T cells." (PMID 39835140, 2024). "By binding to its receptors IL-13Ra1 and IL-13Ra2, it activates downstream signaling cascades, influencing the proliferation, inhibition, or apoptosis of certain tumor cells." (PMID 38519926, 2024). "In in vivo conditions, mice were injected intratumorally with 1 × 105 anti-IL-13Rα2 CAR-T cells, and all of the four CAR-T cells variants showed anti-tumor activity." (PMID 38339374, 2024). "Eligibility for the trial required confirmation of IL-13Rα2 tumor expression, a Karnofsky index of 60 or higher, and a life expectancy of more than four weeks." (PMID 38727262, 2024). "Initial efforts concentrated on IL13Rα2 due to its prevalence in GBMs and its correlation with aggressive tumor behavior and poor prognosis." (PMID 38727262, 2024). "The intracranial administration of IL-13Rα2-specific CAR-T cells into orthotopic GBM mice successfully resulted in tumor regression." (PMID 38486856, 2024). "In contrast, the knockdown of IL-13Rα2 sensitized the cells to doxorubicin, increasing apoptosis and reducing tumor growth in mice." (PMID 39598436, 2024). "Specifically, CAR T-cell therapy targets tumor surface molecules such as epidermal growth factor receptor variant III (EGFR variant III), interleukin 13 receptor subunit alpha 2 (IL13Rα2), and human epidermal growth factor receptor 2 (HER2)." (PMID 39599889, 2024). "This variability in expression profiles, along with the capacity of IL-13Rα2 to influence tumor cell survival and proliferation via receptor signaling mechanisms, renders IL-13Rα2 and EphA-2 promising targets for cancer therapy." (PMID 38612592, 2024). "The receptors EphA-2 and IL-13Rα2 are notably overexpressed on tumor cells in these subtypes compared to normal epithelial cells, suggesting their potential as targets for CAR T-cell therapy." (PMID 38612592, 2024). "In a tumorigenic mice model, knockdown of IL-13Rα2 significantly decreased tumor growth under treatment with doxorubicin in KHOS/NP cells." (PMID 39598436, 2024).
tumor (continued). "The treatment of established IL13Rα2+ KLuc tumors (day 7) with 20 Gy focal radiation showed a strong cytotoxic effect, with tumor reduction observed in all of the mice by BLI." (PMID 38994929, 2024). "These CAR-T cells directly kill tumor cells by targeting IL-13Rα2 and convert TGF-β from an immunosuppressant to an immunostimulant through TGF-β targeting." (PMID 39506843, 2024). "The overexpression and upregulation of IL13Rα2 in different tumor cells make it an appropriate candidate for developing anticancer drugs." (PMID 39118800, 2024). "Despite various targeted strategies against EphA-2 and IL-13Rα2 to curb tumor growth, the efficacy of these interventions remains constrained." (PMID 38612592, 2024). "In a study conducted by Brown and colleagues (NCT02208362), the multi-dose treatment with IL-13Rα2 CAR-T cells led to complete tumor regression for almost 8 months in a patient with GBM." (PMID 39697210, 2024). "We have shown that IL‐13Rα2‐CAR‐T cells are biologically active and functional as they secrete IFN‐γ when exposed to IL‐13Rα2 positive tumour cells." (PMID 38685487, 2024). "The killing of tumour cells was highly specific to the IL‐13Rα2 expression on target tumour cells as gene KD by gene silencing of IL‐13Rα2 on target tumour cells significantly eliminated cytotoxic activity of CAR‐T cells." (PMID 38685487, 2024). "In vivo, a transient anti-tumor response was observed in mice that received a dose of 3 × 106 CAR-T cells targeting one (IL-13Rα2) or two (IL-13Rα2 and Eph2A) antigens." (PMID 38339374, 2024). "IL-13Rα2 is expressed in most patients with diffuse high-grade glioma (HGG) but not in normal brain tissue and it is associated with poor tumor prognosis." (PMID 39506843, 2024). "Further, healthy donor Tn/mem-derived CD19-CAR and IL-13Rα2-CAR-T cell products exhibited improved anti-tumor activity in mice, as compared to Tcm-derived products." (PMID 38454126, 2024). "This review delves into the therapeutic challenges of BCA, emphasizing the roles of interleukin-13 receptor α2 (IL-13Rα2) and erythropoietin-producing hepatocellular receptor A2 (EphA2) in tumor progression and resistance." (PMID 38612592, 2024). "Specifically, in a cohort of 20 primary GBMs, tumours targeting HER2 or IL13Rα2 alone had a near-complete eradication rate of 60%−70%, whereas tumours targeting both HER2 and IL13Rα2 had a rate exceeding 90%." (PMID 38660136, 2024). "Briefly, as previously reported, the murine IL13Rα2-CAR T (mCAR T) consists of the murine IL13 tumor-targeting domain, murine CD8 hinge (mCD8h), murine CD8 transmembrane domain (mCD8tm), murine 4-1BB costimulatory domain (m4–1BB), and murine CD3 zeta (mCD3ζ)." (PMID 38994929, 2024). "To model more tumor-representative conditions, we determined in detail the activity of Pep-1-Phor21 against IL-13Rα2-positive TNBC spheroid cultures." (PMID 37345109, 2023). "IL13RA2 plays an important role in cell migration, contributing to tumor progression, invasion, and metastasis in several cancers." (PMID 37762335, 2023). "When the CAR-Ts were exposed to IL13Rα2-expressing tumour cells, i.e., stimulated with the CAR-target antigen, both CAR[A]-T and CAR[B]-T were less responsive compared to CAR[E]-T." (PMID 37563127, 2023). "The immunohistochemical staining showed that IL-13Rα2 was located in the cytoplasm and/or membrane in a variable number of tumor cells (left column)." (PMID 37158824, 2023). "This study demonstrates that the CAR T-cells directly target tumor cells through IL13Rα2 and stimulate an innate immune response." (PMID 38002496, 2023). "Which checkpoint inhibitor improved therapy the most was dependent on which CAR T cell was used, as CAR T cells targeting EGFRvIII and IL13Rα2 both induced different checkpoint milieus in their respective tumor microenvironments." (PMID 36900205, 2023). "After injecting CAR T cells into the tumor cavities, a reduction in tumor volume was noted, implying the antitumor activity of IL13Rα2-CART cells." (PMID 37445721, 2023).
tumor (continued). "Originally believed to act as a decoy receptor, IL13Rα2 signals via STAT6-independent pathways to promote tumour cell survival, invasiveness, metastasis and the production of transforming growth factor (TGF)-β, ultimately driving fibrosis." (PMID 36829563, 2023). "In conclusion, we have uncovered the participation of SNH3 in the IL-13/IL13Rα2/PTP1B pathway to promote tumor growth and invasion." (PMID 37963919, 2023). "Intracranial delivery of IL-13Rα2-directed CAR-T cells into the resection cavity of three patients with recurrent GBM led to a transient anti-tumor response in two patients, as indicated by an increased MRI gadolinium enhancement and increased FLAIR signal." (PMID 37443804, 2023). "Intriguingly, tumor cells with low IL13Rα2 expression evaded treatment with IL13Rα2-redirected CAR T cells and continued to proliferate, contributing to tumor recurrence." (PMID 38067356, 2023). "This approach was tested for targeting HER2 and IL-13Rα2 in an orthotopic xenogeneic GBM mouse model with the use of intratumoral injections: TanCAR-T cells showed enhanced anti-tumor efficacy and improved animal survival." (PMID 37443804, 2023). "In brain slices from a GBM6 tumor-bearing mice model six days after the injection of α-EGFRvIII synNotch–α-EphA2/IL13Rα2 CAR-T cells, primed T cells and apoptosis cells can be detected only in tumor sites." (PMID 36983174, 2023). "One patient with multifocal leptomeningeal disease characterised by heterogenous IL13Rα2 expression underwent resection of three of five tumours, after which six doses of CAR T-cells were administered using the intracavitary route each week." (PMID 36829563, 2023). "Taken together, our results reveal that the transcription factor SHN3 is a key mediator of the tumor-promoting IL-13/IL13Rα2/PTP1B signaling pathway." (PMID 37963919, 2023). "For example, a recurrent GBM (rGBM) patient obtained tumor intracranial and spinal regression after intracranial administration of IL-13Rα2-targeted CAR-T cells, but IL-13Rα2-negative tumors resulted in a subsequent relapse." (PMID 36923402, 2023). "This treatment was well tolerated with only temporary CNS inflammation reported, despite only two patients exhibiting anti-tumour responses, either through reduced IL13Rα2 expression or an increased necrotic tumour volume at delivery site." (PMID 37686652, 2023). "For example, the tumor-specific antigen EGFRvIII is activated by the SynNotch receptor to induce local CAR expression, which is then coupled with EphA2 and IL13Rα2 to induce tumor cell recognition and killing." (PMID 36707873, 2023). "According to clinical data, the tumor microenvironment responds to IL13Rα2 CAR T therapy by boosting CD3+, CD14+, and CD15+ immune cells as well as inflammatory cytokines after locoregional CAR infusion." (PMID 36721153, 2023). "Encouragingly, early indicators of anti-glioma activity were observed, including a rapid increase in necrotic tumor volume on MRI, a notable reduction in IL-13Rα2 tumor cell expression, and a promising extension of OS." (PMID 37900496, 2023). "Encouragingly, this modulation of IL-13Rα2 expression was only demonstrable in malignant cells, pointing to potentially specific tumor cell targeting when using Pep-1-Phor21 in combination with epigenetically active anti-cancer compounds." (PMID 37345109, 2023). "Taken together, the results show that TNBC cells, in particular, express relatively high levels of IL-13Rα2 and the Pep-1-Phor21 peptide efficiently targets these tumor cells, rapidly destroying them through cytolysis." (PMID 37345109, 2023). "Recurrent tumors appeared outside the brain with lowered expression of IL13Rα2 highlighting antigen escape as a mode of tumor resistance to immunotherapy." (PMID 36721153, 2023). "The moderate anti-tumor efficacy of GB-13 across multiple IL-13Rα2-expressing HGG models provides some support for an early-phase clinical trial in patients with upregulated IL-13Rα2 expressing tumors." (PMID 35631512, 2022).
tumor (continued). "IL-13 can also bind to IL-13Rα2 on tumor cells and enhance tumor invasion and metastasis through activating ERK/activator protein 1 (AP-1) signaling and matrix metalloproteinases." (PMID 35721518, 2022). "IL-13Rα2 is a cancer-germline antigen present in more than 70% of GBM tumors, associated with tumor invasiveness and poor prognosis." (PMID 35628161, 2022). "Given the cell line-dependent overexpression of IL-13Rα2 in our DMG and adult GBM tumor cell models, we investigated the role of IL-13Rα2 signaling in HGG." (PMID 35631512, 2022). "Vaccination with IL-13Rα2 DNA significantly reduced murine syngeneic tumor growth through induction of T and B cell responses." (PMID 35464460, 2022). "The tumour relapsed 7.5 months after the first CAR injection and analysis of the post-treatment biopsy showed the loss of IL13Ra2." (PMID 35454848, 2022). "Peptides targeting IL-13Rα2 can be used to block native ligand-receptor interaction/signaling and/or deliver conjugated therapeutic agents to the tumor microenvironment (TME)." (PMID 35464460, 2022). "Lower or heterogeneous expression of target antigens on tumor cells was documented in treatments with anti-EGFRvIII- and IL13Ra2-CAR-T cell therapies and anti-CD19/CD3 BiTE (blinatumomab)." (PMID 36419058, 2022). "Anti-tumor effects of GB-13 strongly correlated with IL-13Rα2 expression and were reflected in apoptosis induction and decreased cell proliferation in vitro." (PMID 35631512, 2022). "Such an efficient delivery to tumor related markers have been confirmed in GBM tumors where IL13Rα2 is actively involved." (PMID 35612318, 2022). "Given its differential expression in tumor versus normal tissue, IL-13Rα2 is an attractive immunotherapy target, as both a targetable receptor and an immunogenic antigen." (PMID 35464460, 2022). "YYB103 is a newly developed CAR-T cell targeting IL-13RA2, which was demonstrated to inhibit tumor growth and prolong the overall survival of U87 MG xenogeneic animal models." (PMID 36466873, 2022). "Direct intratumoral administration of GB-13 via convection-enhanced delivery (CED) significantly decreased tumor burden and resulted in prolonged survival in IL-13Rα2-upregulated orthotopic xenograft models of HGG." (PMID 35631512, 2022). "The delivery method, as for the IL13Rα2 studies, was either by direct injection into the tumour resection cavity or by intraventricular delivery." (PMID 36505819, 2022). "Anti-tumor efficacy was enhanced with IL-13Rα2 DNA priming plus a protein/adjuvant boost consisting of the extracellular domain of IL-13Rα2 protein, CpG, and incomplete Freund’s adjuvant (IFA)." (PMID 35464460, 2022). "Compared with individual or pooled monospecific CAR T cells, HER2/IL-13Rα2 CARs improved tumor control and survival in a human orthotopic GBM model." (PMID 35464460, 2022). "IL-13 sequestration by IL13α2 within tumour cells results in tumour cell escape from apoptosis, while knocking down IL13Rα2 promotes GBM cell apoptosis." (PMID 34868634, 2021). "Second, subjects with medium and high IL-13Rα2 expression had a higher incidence of a new tumor events than subjects with low IL-13Rα2 expression." (PMID 33591997, 2021). "Brown and colleagues designed a 4-1BB (CD137) co-stimulatory CAR (IL13BBѯ) and a manufacturing platform using enriched central memory T cells to confirm that IL13Ra2-targeted CAR-T enhanced anti-tumor effect sin patient-derived tumor models." (PMID 34248623, 2021). "Recently, we have demonstrated that IL-13Ra2 is expressed in invading tumor cells in the perineural invasion of PDA and its expression is associated with the histologic type and the clinical stage of the disease." (PMID 34201539, 2021). "Bi-specific CAR T cells expressing both HER2 and IL13Rα2 displayed increased tumor elimination compared to singular TA-specific CAR T cells in a murine model of GBM." (PMID 34113233, 2021).
tumor (continued). "On the other hand, IL-13 binds to IL-13Rα2 with high affinity and can mediate signal transduction through this chain in diseased fibroblasts and tumor cells." (PMID 33591997, 2021). "There were more post-operative tumor recurrences, and survival of subjects was significantly shortened in the group with high IL-13Rα2 expression." (PMID 34201539, 2021). "In another study using the mouse model, it was demonstrated that two kinds of humanized scFv based chimeric antigen receptor (CAR) T cells targeting IL13Rα2 inhibited tumor growth in vitro and in vivo." (PMID 33917914, 2021). "The distribution of tumor-specific antigens, such as IL-13Rα2, Her2, and EGFRvIII, is heterogeneous in GB, and they are expressed to different degrees at different time points during CAR-T cell therapy." (PMID 33741903, 2021). "In contrast, the gene silencing of IL-13Rα2 by siRNA technology ameliorated tumor invasion and metastasis." (PMID 34201539, 2021). "Co‐targeting HER2, IL13Rα2, and EphA2 have been found to overcome interpatient variability by a tendency to capture nearly 100% of tumor cells in most tumors tested in this cohort." (PMID 34145792, 2021). "A new tumor event occurred significantly more frequently in ACC subjects with medium (58%) (p = 0.0202) or high (62%) (p = 0.0042) IL-13Ra2 expression compared to low (26%) IL-13Ra2 expression." (PMID 33591997, 2021). "Using a reporter gene system, preliminary clinical evidence supports trafficking of intracerebrally administered anti-IL13Rα2 CAR T cells to the tumor region using [18F]FHBG PET-based imaging." (PMID 34298615, 2021). "We found that YYB-103 CAR T cells showed effective cytotoxicity toward tumor cells expressing IL13Rα2." (PMID 34819930, 2021). "Different tumour antigens that have been targetted in CAR-T clinical trials in GBM include IL13Rα2, EGFRvIII, and Her2." (PMID 33572301, 2021). "Upregulation of IL-13Rα2 has been detected in cancer cells, which facilitates tumor growth and metastasis." (PMID 34769439, 2021). "Reduction of IL‐13Rα2 tumor cell expression was recorded in one patient, with a significant increase in the volume of necrotic tissue volume." (PMID 34145792, 2021). "The immunohistochemical staining for IL13Rα2 was seen in tumor cells of all histologic subtypes of RCC." (PMID 33917914, 2021). "The binding of IL-13 with its cognate receptor, interleukin-13 receptor subunit alpha-2 (IL-13Rα2), has a mechanistic role in tumor growth, invasion, and metastasis via phosphorylation and activation of PI3K, Akt, and mTOR proteins." (PMID 34439380, 2021). "In another way, the upregulation of IL-13Rα2 by plasmid vector in the IL-13Rα2-negative tumor resulted in enhanced tumor progression." (PMID 34201539, 2021). "IL13-PE was highly selective and potent for killing human tumor cells in vitro, in particular glioblastoma cells that expressed high levels of IL-13Rα2 chain." (PMID 32957689, 2020). "Due to its antiapoptotic and tumor-growing activity in IL-13Rα2-bearing cells, IL-13Rα2 has been proposed as a new oncogene." (PMID 33233582, 2020). "Trivalent CAR T cells, targeting HER2, IL13-Rα2, and EphA2, exhibited excellent anti-tumor activity in vitro in the GBM model." (PMID 33224149, 2020). "Preclinical studies investigating these CARs, show anti-tumor efficacy and low on-target/off-tumor toxicity after intracranial delivery, due to the abscence of IL13RA2 expression in normal brain tissue." (PMID 32983080, 2020). "Building on these results, the modified IL13Rα2-targeted CAR T cells were further reported to improve anti-tumor potency and T cell persistence by 4-1BB co-stimulation and IgG4-Fc linker mutation." (PMID 33228738, 2020). "The IL-13Rα2 chain is also highly expressed by several tumor cells and binds with higher affinity to IL-13 than the other chain (IL-13Rα1), even when coupled to IL-4Rα." (PMID 33233582, 2020).